FUS (FUS RNA binding protein)
Diseases named in the same sentence as FUS in open-access papers (continued):
Sharing a sentence is not in itself a finding about the gene and the disease.
motor neuron degeneration (13 papers, 2013 to 2024). "Similar to TDP-43, the proteinopathy of mutant FUS proteins is characterised by the cytosolic accumulation of toxic FUS aggregates alongside a loss of wild-type proteins, dysfunctional mRNA metabolism and motor neuron degeneration." (PMID 38203614, 2023). "Mutations in the FUS gene cause rare forms of ALS (ALS-FUS) in which motor neuron degeneration is associated with FUS immunoreactive inclusions." (PMID 24027631, 2013). "It was previously reported that increased levels of FUS in vivo, either by overexpression or disruption of regulatory circuits, are associated with progressive motor neuron degeneration and ALS and suggested that phase separation of FUS in the cytoplasm, followed by aggregation, drives disease." (PMID 34233002, 2021). "Several genes mutated in ALS patients and implicated in motor neuron degeneration have been studied in zebrafish, including superoxide dismutase (SOD1), alsin (ALS2), the elongated protein 3 (ELP3), FUS, and TDP-43." (PMID 33499374, 2021). "First, genetic mutations that alter or truncate the nuclear localization signal (NLS) of FUS and thus cause impaired nuclear import of FUS, cause familial ALS21–24 or motor neuron degeneration in mice." (PMID 29728564, 2018). "Furthermore, SMA mutations in the tudor domain of SMN, which is crucial for binding to Sm proteins, abolished SMN association with TDP-43 and FUS/TLS, supporting an importance of SMN/TDP-43/FUS complex in the biogenesis of spliceosome and in motor neuron degeneration." (PMID 23255347, 2013). "Motor neuron degeneration involving TDP-43, FUS, and SOD1 remains a central theme in ALS research." (PMID 39659885, 2024). "This is consistent with the absence of motor phenotypes in Fus knock-out mice, showing that even the complete absence of the FUS protein is not sufficient to trigger motor neuron degeneration." (PMID 28243725, 2017).
acute myeloid leukemia (12 papers, 2008 to 2025). Acute myeloid leukemia (AML) is a group of neoplasms arising from precursor cells committed to the myeloid cell-line differentiation. "The involvement of the ERG in gene translocation (EWS-ERG and TLS/FUS-ERG) and the high expression of ERG are implicated in cancer, including Ewing’s sarcoma and acute myeloid leukemia, in addition to PCa." (PMID 36430730, 2022). "In the present study, we applied RNA-Seq methodology to an acute myeloid leukemia with a rather complex karyotype and identified a cryptic FUS/ERG fusion gene." (PMID 24068373, 2013). "We compared these changes to those induced by FLI1 and ERG1 alone as well as to those induced by an isoform of FUS-ERG associated with acute myeloid leukemia (AML) but not ESFT." (PMID 18648544, 2008). "In acute myeloid leukemia (AML), a small subset of patients have t(16:21) ERG:FUS fusion, which was first identified in 1994 as a driver of leukemogenesis." (PMID 38933637, 2024).
Cognitive impairment (12 papers, 2017 to 2026). Abnormal cognition is characterized by deficits in thinking, reasoning, or remembering. "Cognitive impairments associated with mutant FUS expression (as we previously reported) were significantly aggravated 6 months post-injection." (PMID 38862967, 2024). "Apart from the typical ALS phenotype, patients with p.P525L mutation in the FUS gene can present with great clinical heterogeneity including tremor, movement disorders, dropped‐head syndrome, and cognitive impairments." (PMID 32307925, 2020). "Loss of FUS also promotes the pathological splicing of tau, and this has been suggested to contribute to accumulation of phosphorylated tau – along with neurodegeneration and cognitive defects – upon genetic silencing of FUS in the brain of mice." (PMID 40468389, 2025). "Taken together, our findings suggest that disease-linked mutation in FUS may lead to changes in proteostasis and mitochondrial dysfunction, which in turn affect brain structure and connectivity resulting in cognitive deficits." (PMID 33407930, 2021). "Hence, our findings suggest that disease-linked mutation in FUS may lead to changes in proteostasis and mitochondrial dysfunction that in turn affect brain structure and connectivity resulting in cognitive deficits." (PMID 33407930, 2021). "Furthermore, a mutation in a truncated protein lacking a nuclear localization signal was identified to cause juvenile ALS with rapid disease progression and cognitive impairment, suggesting that impaired nucleocytoplasmic trafficking of FUS alone can lead to the ALS phenotype." (PMID 28928015, 2017). "In contrast to fALS associated with variants in e.g. C9ORF72, FUS, or TARDBP, there is hardly any cognitive impairment in SOD1-associated ALS70." (PMID 39366938, 2024). "Specifically, our data suggest that disease-linked mutation in FUS may lead to change in nonsense-mediated decay (NMD), proteostasis and mitochondrial functions, which in turn affect brain structure and connectivity resulting in cognitive deficits." (PMID 33407930, 2021). "To these preceding efforts, we report that age-dependent motor and cognitive deficits develop in humanized mutant FUS mice without detectable human FUS cytoplasmic aggregation." (PMID 30344044, 2018).
cervical cancer (11 papers, 2020 to 2024). A primary or metastatic malignant neoplasm involving the cervix. "CircRNA_0000285 was aberrantly highly expressed in cervical cancer tissues, induced proliferation and migration of cervical cancer cells through regulation of FUS." (PMID 37667251, 2023). "Studies have shown that lncRNA XIST promotes cervical cancer progression by upregulating FUS via competitively binding to miR-200a." (PMID 36879084, 2023). "For example, circRNA_0000285 can promote the proliferation and metastasis of cervical cancer cells by upregulating FUS, and circRNA_100876 can increase the growth of colorectal cancer cells by inhibiting the miR-516b expression." (PMID 35543347, 2022). "The hnRNP P2 (FUS/TLS) is highly expressed in cervical cancer as well as in SiHa and HeLa cells, dependently from the activation of XIST lncRNA/miR-200a axis, and induces the epithelial mesenchymal transition phenotype and proliferation while inhibiting apoptosis in cervical cancer cells." (PMID 32596243, 2020). "Our data indicated that ABHD11-AS1 promoted cervical cancer progression by activating EGFR signaling, preventing FUS-mediated degradation of ABHD11 mRNA." (PMID 38146687, 2023).
myoepithelioma (10 papers, 2011 to 2024). "FUS gene rearrangements have also been reported in some myoepitheliomas." (PMID 31915021, 2020). "No rearrangement of the EWSR1 and FUS loci was detected as reported in myoepitheliomas." (PMID 29992069, 2018). "By using fluorescence in situ hybridization for CCND1 and FUS, respectively, no breaks in these genes could be detected in chondroid lipoma or in myoepithelioma." (PMID 21559269, 2011). "FISH studies, performed to rule out the possibility of gastrointestinal clear cell sarcoma and a myoepithelial tumor, showed no rearrangement of the EWSR1, FUS, ATF1, and CREB1 genes." (PMID 35001360, 2022). "Myoepithelial neoplasms (MN) are rare and not well-circumstanced entities displaying a heterogeneous spectrum of genetic abnormalities, including EWSR1, FUS and PLAG1 rearrangements." (PMID 28947952, 2017).
glioblastoma (9 papers, 2018 to 2025). The most malignant astrocytic tumor (WHO grade IV). "For example, ADAMTS9-AS2 was increased in TMZ-resistant glioblastoma cells to enhance chemoresistance by upregulating the FUS/MDM2 axis." (PMID 36816363, 2023). "LncRNA rhabdomyosarcoma 2 associated transcript (RMST) enhances FUS SUMOylation, which contributes to the interaction between FUS and hnRNP D to suppress glioblastoma cell mitophagy." (PMID 36911524, 2023). "For example, circPTN sponges miR-145-5p/miR-330-5p to promote proliferation and stemness in glioblastoma; FUS/circ_002136/miR-138-5p/SOX13 feedback loop regulates angiogenesis in glioblastoma." (PMID 32308563, 2020). "In U-251 glioblastoma cells, the pro-survival and pro-migration effects of RMST have been attributed to its direct interaction with fused in sarcoma (FUS) a DNA/RNA binding protein that is involved in mRNA transcription, maturation, and transport that promotes cell migration and proliferation." (PMID 34744768, 2021). "For example, linc00470 binds to FUS and AKT to form a ternary complex, anchoring FUS in the cytoplasm to increase AKT activity, which was found to inhibit the ubiquitination of HK1, affect glycolysis, and inhibit autophagy in glioblastoma cells." (PMID 30134946, 2018).
Lewy body dementia (9 papers, 2014 to 2025). A progressive form of dementia characterized by the presence of protein deposits called Lewy bodies in the midbrain and cerebral cortex, and loss of cholinergic and dopaminergic neurons. "These neurodegenerative diseases are characterized by the appearance of the following specific protein inclusions: amyloid beta and tau in AD; α-synuclein in Lewy body dementia; and tau, TDP-43, or FUS in frontal-temporal dementia." (PMID 28082867, 2016). "Alzheimer’s disease (AD), dementia with Lewy bodies (DLB), and frontotemporal lobar degeneration (FTLD) develop in the elderly population and share the accumulation of pathological proteins (tau and amyloid-β in AD, α-synuclein in DLB, and TDP-43, tau, and FUS in FTLD)." (PMID 34880745, 2021).
mesenchymal tumors (9 papers, 2019 to 2025). "Myoepithelial tumor of soft tissue is a rare mesenchymal tumor with characteristic gene fusion involving the EWSR1 or FUS gene in about 50% of cases." (PMID 40978976, 2025). "Myoepithelial tumors of soft tissue are mesenchymal tumors with characteristic gene fusions involving the EWSR1 or FUS gene in many cases." (PMID 40978976, 2025). "All these observations underline the morphological and immunophenotypic heterogeneity of EWSR1/FUS-CREM fusion driven mesenchymal neoplasms." (PMID 34228212, 2022). "Fusions between the FET gene family (EWSR1 and FUS) and one of the CREB transcription factor family members (ATF, CREB1, and CREM) have been increasingly reported in a variety of mesenchymal neoplasms that are clinically, anatomically, and phenotypically distinct." (PMID 40748380, 2025). "EWSR1/FUS-CREM fusions were recognized recently in a group of unclassified epithelioid mesenchymal neoplasms showing predilection for intra-abdominal organs, not fitting any known EWSR1-CREB-rearranged entity." (PMID 34228212, 2022). "There are still very few reports of gastric epithelioid mesenchymal tumors with EWSR1/FUS::CREB fusion that do not fit the criteria for GNETs, and the collection of additional cases is needed to better understand their epidemiology, symptoms, prognosis, and treatment." (PMID 40242428, 2025).
synucleinopathies (8 papers, 2016 to 2025). "Aberrant RNA processing has been increasingly linked to synucleinopathies, where α-synuclein interacts with RNA-binding proteins such as TDP-43, FUS, and hnRNPs, disrupting splicing, RNA stability, and translation." (PMID 41303651, 2025). "Morphology and anatomical distribution of pathological alterations still predominates the classification of AD, α-synucleinopathies, TDP-43 and FUS/FET proteinopathies." (PMID 26848654, 2016).
essential tremor (7 papers, 2014 to 2021). A relatively common disorder characterized by a fairly specific pattern of tremors which are most prominent in the upper extremities and neck, inducing titubations of the head. "Recently, a mutation located in the nuclear export signal (NES) of the FUS gene has been reported to cause an autosomal dominant form of familial Essential tremor." (PMID 25375143, 2014). "Linkage studies conducted in families with ET have reported mutations in ETM2 (essential tremor monogenetic locus 2) and (fused in sarcoma) FUS, while other studies have linked (leucine-rich repeat and Ig domain containing 1) LINGO1, FUS and teneurin transmembrane protein 4 (TENM4) with ET3." (PMID 29593234, 2018). "Haploinsufficiency mutations involving FUS and that lead to nonsense-mutation-mediated mRNA decay were identified in an essential-tremor-affected family that did not reveal any signs of ALS40." (PMID 29203801, 2017).
gastric cancer (7 papers, 2007 to 2025). A primary or metastatic malignant neoplasm involving the stomach. "While on the contrary, silencing of FUS activates cell apoptosis in gastric cancer." (PMID 36263181, 2022). "On the contrary, its embedded miR-2682-3p could disturb the function of MIR137HG to gastric cancer by holding the same target FUS." (PMID 35733138, 2022). "Our study illustrated long non-coding RNA MIR137HG could promote the progression of gastric cancer through interacting with FUS and affecting a series of its downstream molecules (MET, RHOC, and CTNNB1." (PMID 35733138, 2022). "In gastric cancer, DLX6-AS1 modulates FUS expression, which in turn enhances MAP4K1 mRNA stability through interaction with the FUS protein." (PMID 41034525, 2025). "For instance, LBX2-AS1 is up-regulated in gastric cancer and silencing LBX2-AS1 restrains proliferative, migratory, and invasive capacities of gastric cancer cells by miR-491-5p/ZNF703, miR-219a-2-3p/FUS or miR-4766-5p/CXCL5 axis." (PMID 34552959, 2021). "lncRNA-MIR137HG promoted growth and metastasis in gastric cancer by interacting with FUS, while miR-2682-3p could inhibit the function of MIR137HG via the same target FUS." (PMID 35733138, 2022). "In conclusion, MIR137HG, miR-2682-3p, and FUS formed a negative feedback loop to regulate gastric cancer progression." (PMID 35733138, 2022).
round cell liposarcoma (7 papers, 2013 to 2025). A poorly differentiated liposarcoma, characterized by the presence of solid sheets of primitive round mesenchymal cells and the absence of myxoid stroma. "The presence of DDIT3 gene alteration can aid in diagnosing myxoid/round cell liposarcoma (with over 95% of cases showing CHOP/FUS fusion)." (PMID 40308488, 2025). "On the other hand, the DDIT3 gene is known to be rearranged in myxoid/round cell liposarcomas, which can fuse with either EWSR1 or FUS, and these fusions serve as diagnostic markers for this entity." (PMID 38275873, 2024). "For example, FUS and DNA damage-inducible transcript 3 are able to form a fusion oncogene FUS-CHOP, which increases the invasive capability of human mucus-like and round cell liposarcoma cells." (PMID 30736838, 2019).
angiomatoid fibrous histiocytoma (6 papers, 2011 to 2021). "For instance, EWSR1 or FUS can fuse to ATF1 or CREB1 in clear cell sarcoma of soft tissue as well as angiomatoid fibrous histiocytoma." (PMID 34081036, 2021). "Angiomatoid fibrous histiocytoma, primary pulmonary myxoid sarcoma, and myoepithelial tumours of soft tissue are exceptionally rare forms of sarcoma that harbour translocations of the EWSR1 gene (EWSR1-CREB, EWSR1-ATF1) or the FUS gene (FUS-AFT1)." (PMID 33669307, 2021).
colorectal cancer (6 papers, 2021 to 2023). A primary or metastatic malignant neoplasm that affects the colon or rectum. "Mechanism studies show that FUS regulates the metastasis of colorectal cancer cells by interacting with the reverse complementary matches of circLONP2 to regulate the biogenesis of circLONP2." (PMID 34439339, 2021). "In primary colorectal cancer tissues, the expression of CircLONP2 is significantly up-regulated, and the expression of CircLONP2 is positively correlated with the mRNA level of FUS." (PMID 34439339, 2021). "Loss of FUS function leads to impaired cellular proliferation and marked increases in phosphorylated histone H3, whereas APOC1 promotes tumor progression via MAPK signaling as shown for colorectal cancer and maintains cell survival by preventing apoptosis." (PMID 37208732, 2023).
fragile X syndrome (6 papers, 2010 to 2023). A genetic syndrome caused by mutations in the FMR1 gene which is responsible for the expression of the fragile X mental retardation 1 protein. "FMRP and FUS, genetically linked to Fragile-X syndrome and ALS respectively, are two multifunctional RBPs involved in post-transcriptional gene expression." (PMID 36702823, 2023). "There are other examples of RBPs involved in neurological disease, including FMRP (related to Fragile X syndrome) and FUS (associated with ALS/FTD)." (PMID 33363456, 2020).
spinocerebellar ataxia (6 papers, 2010 to 2025). "Extensive genetic testing has been performed in various cases, which included ALS genes (C9orf72, FUS, SOD1, TARDBP), oculopharyngeal muscular dystrophy (PABPN1), Kennedy disease (AR), panels for spinocerebellar ataxia as well as whole-exome sequencing." (PMID 33842068, 2021).
viral infection (6 papers, 2013 to 2023). "Therefore, we hypothesized that viral infections might similarly induce cytoplasmic retention of FUS, which could exacerbate the effects of the P525L mutation." (PMID 31695598, 2019). "Based on our data, we propose a model whereby a viral infection involving dsRNA response can serve as a trigger, or second hit, for FUS proteinopathy in humans." (PMID 31875556, 2019). "Since ALS-associated RBPs such as FUS and TDP-43 are ubiquitously expressed, it is conceivable that viral infections in immune cells could exacerbate ALS pathogenesis and spread to neurons via prion-like spreading." (PMID 31695598, 2019). "In addition, numerous ALS-associated proteins have been shown to either directly interact with viral nucleic acids or to regulate the cellular response to viral infection, including FUS, hnRNPA1, hnRNPA2, SETX, TBK1, and TDP-43." (PMID 31695598, 2019). "Altogether, these results support the hypothesis that SNs with mutant FUS are under stress from the ALS mutation, and the addition of a viral infection increases the risk of degeneration compared with WT." (PMID 31695598, 2019). "Another possibility is that neurons with mutant FUS are already under significant stress due to the disruption of many RNA-binding proteins, suggesting that an additional stress such as viral infection is sufficient to unmask ALS phenotypes in SNs with genetic ALS mutations." (PMID 31695598, 2019). "Viral infection can serve as a trigger of FUS proteinopathy in ALS." (PMID 31875556, 2019). "However mutations in genes such as copper/zinc superoxide dismutase (SOD1), fused in sarcoma (FUS) and TAR DNA binding protein (TARDBP), have also been described in SALS patients; also environmental causes such as smoking and viral infection are linked to ALS." (PMID 23533690, 2013). "Next, to confirm whether IFNβ overproduction during viral infection is a common phenomenon in all ALS patients, we examined IFNβ production by cells from several ALS patients with mutations in the ALS-causative genes, SOD1, FUS, ANG, FIG4, and TARDBP." (PMID 37352136, 2023).
juvenile amyotrophic lateral sclerosis (5 papers, 2020 to 2025). Juvenile amyotrophic lateral sclerosis (JALS) is a very rare severe motor neuron disease characterized by progressive upper and lower motor neuron degeneration causing facial spasticity, dysarthria, and gait disorders with onset before 25 years of age. "Here, a de novo mutation c.1509dupA (p.R503fs) in fused in sarcoma (FUS) was detected in a patient with sporadic juvenile amyotrophic lateral sclerosis (JALS)." (PMID 33093822, 2020). "Fused in sarcoma (FUS) mutations represent the most common genetic etiology of juvenile amyotrophic lateral sclerosis (JALS), for which effective treatments are lacking." (PMID 38711616, 2024).